MIR4283-2 (microRNA 4283-2)
Synonyms: hsa-mir-4283-2
Gene: MicroRNA gene on chromosome 7 (63,621,090 to 63,621,169, forward strand). Ensembl gene ENSG00000265214.
Homologues: Paralogues in human: MIR4283-1 (100% identical).